BTNL2 (butyrophilin like 2)
Diseases named in the same sentence as BTNL2 in open-access papers (continued):
Sharing a sentence is not in itself a finding about the gene and the disease.
tumor (10 papers, 2021 to 2025). "We then explored the impact of genetic BTNL2 deficiency on anti-tumour immune responses." (PMID 35017553, 2022). "The antibody-mediated blockade of BTNL2 attenuated tumor progression in multiple in vivo murine tumor models, resulting in the prolonged survival of tumor-bearing mice." (PMID 37240071, 2023). "We also performed intravenous injection of MC38 and CT26 cells, and found that survival of tumour-bearing mice was significantly extended by anti-BTNL2 mAb treatment compared to controls." (PMID 35017553, 2022). "We detected a substantial decrease in tumour infiltration by neutrophils following anti-BTNL2 mAb treatment compared with controls." (PMID 35017553, 2022). "There was no detectable difference in tumour growth between BTNL2-KO LLC tumours implanted in control mice or BTNL2-KO mice." (PMID 35017553, 2022). "Mechanistically, BTNL2 interacts with local γδ T cell populations to promote IL-17A production in the tumour microenvironment." (PMID 35017553, 2022). "Consistently, BTNL2-KO LLC tumours had significantly fewer numbers of infiltrating γδT17 cells and MDSCs, and conversely higher numbers of infiltrating CD8+IFN-γ+ T cells, as compared to wild-type LLC tumours." (PMID 35017553, 2022). "Antibody-mediated blockade of BTNL2 attenuates tumour progression in multiple in vivo murine tumour models, resulting in prolonged survival of tumour-bearing mice." (PMID 35017553, 2022). "In the A20 tumour model, five out of seven mice demonstrated a complete response with regression of all macroscopic tumour burden following anti-BTNL2 mAb treatment." (PMID 35017553, 2022). "Very recently a mechanism of immune evasion by expression of BTNL2 on cancer cells was described, where BTNL2 promotes IL-17 production by a local γδ T cell population which enhances tumor resistance by recruitment of myeloid suppressor cells T cells." (PMID 35371078, 2022). "To further confirm the important role of IL-17A in the BTNL2 blockage, we purified murine IL-17A-Fc recombinant proteins, and found that treatment with recombinant IL-17A-Fc also abolished the anti-tumour effect of BTNL2 blockade." (PMID 35017553, 2022). "Next, we found that combinational treatment with anti-BTNL2 mAb and anti-PD-1 mAb had an additive anti-tumour effect compared to a single treatment, and anti-BTNL2 mAb and anti-PD-1 mAb had similar anti-tumour effects." (PMID 35017553, 2022). "Strikingly, both intraperitoneal (i.p.)and intravenous (i.v.)delivery of anti-BTNL2 mAb to tumour-bearing mice significantly reduced Lewis lung cancer (LLC) tumour growth." (PMID 35017553, 2022). "To further examine the role of IL-17A in tumour regression following BTNL2 blockade, we neutralized IL-17A in tumour-bearing mice and found that this completely abolished the anti-tumour effect of BTNL2 blockade." (PMID 35017553, 2022). "To further examine the role of MDSCs in the anti-tumour effect of BTNL2 blockade, we depleted MDSCs in tumour-bearing mice using CD11b neutralizing antibodies, but did not utilize anti-Gr-1 mAb, as we detected CD8+ lymphocytes expressing Ly6C in the TME." (PMID 35017553, 2022). "Here, we have demonstrated that BTNL2 is a potent suppressor of anti-tumour immunity, and acts via a previously unreported role in the regulation of γδT17 cells." (PMID 35017553, 2022). "Blockage of BTNL2 with a novel monoclonal neutralizing antibody has a significant therapeutic effect for multiple mice tumours, and has a synergistic effect with anti-PD-1 blockage." (PMID 35017553, 2022). "Following intravenous delivery of A20 tumour cells, a model of widely metastatic disease burden, anti-BTNL2 mAb substantially prolonged the survival of tumour-bearing mice." (PMID 35017553, 2022). "Here we show that butyrophilin-like protein 2 (BTNL2) is a potent suppressor of the anti-tumour immune response." (PMID 35017553, 2022).
tumor (continued). "In this study, we provide evidence that BTNL2 inhibits anti-tumour immunity by acting on local γδ T cell populations to promote IL-17A production, which enhances tumour immune resistance via recruitment of MDSCs." (PMID 35017553, 2022). "Depletion of MDSCs completely abolished the previously observed increase in CD8+IFN-γ+ T cell tumour infiltration as well as the therapeutic anti-tumour effect of BTNL2 blockade." (PMID 35017553, 2022). "Together, these data indicate that tumour cell-autonomous expression of BTNL2 plays a major role in tumour escape from immunosurveillance in the TME, and we think that the non-tumour cell-expressed BTNL2 plays a less important role in this process." (PMID 35017553, 2022). "Consistent with our prior findings, these data further confirmed that Vγ1 γδ T cells were the major IL-17A-producing γδ T cells in tumours, and the anti-tumour effect of BTNL2 blockade was dependent on the regulation of Vγ1 γδT17 cells." (PMID 35017553, 2022). "Here authors show that BTNL2 expression on cancer cells generates a dysfunctional tumour immune microenvironment via promoting IL-17A-producing γδ T cells." (PMID 35017553, 2022). "Inhibition of BTNL2 reduces the number of tumour-infiltrating IL-17A-producing γδ T cells and myeloid-derived suppressor cells, while facilitating cytotoxic CD8+ T cell accumulation." (PMID 35017553, 2022). "Butyrophilin-like protein 2 (BTNL2) is highly expressed in many human tumor samples, BTN/BTNL can bind to the Vγ chain in γδTCR, and the interaction may affect TCR signal transduction." (PMID 36793048, 2023). "Driven by BTNL2, γδT17 cells secrete IL-17A and recruit myeloid suppressor cells, resulting in an increase in the number of TME mesenchymal stem cells, M2 macrophages and tumor-associated macrophages (TAMs)." (PMID 36793048, 2023). "Likewise, murine BTNL2 has been demonstrated to function as a potent suppressor of the anti-tumor immune response." (PMID 37240071, 2023). "Thus, our results suggest that BTNL2 is a negative regulator of anti-tumour immunity and a potential target for cancer immunotherapy." (PMID 35017553, 2022). "Next, we assessed the expression of BTNL2 in the mouse tumour microenvironment (TME)." (PMID 35017553, 2022). "Given the compelling human genetic and translational data in the literature, we hypothesized that antibody-mediated blockade of BTNL2 would enhance the anti-tumour immune response." (PMID 35017553, 2022). "Depletion of Vγ1 γδ T cells also had a therapeutic effect on subcutaneous tumours, and following Vγ1 γδ T cell depletion the anti-tumour effect of BTNL2 blockade was comparable to that of controls, which indicates that the anti-tumour effect of BTNL2 blockade is dependent upon Vγ1 γδ T cells." (PMID 35017553, 2022). "Following depletion of CD8+ T cells in tumour-bearing mice using anti-CD8a neutralizing antibody, the anti-tumour effect of anti-BTNL2 treatment was completely abolished, indicating that CD8+ T cells are the major tumour-cytotoxic cell following BTNL2 blockade." (PMID 35017553, 2022). "It was reported that there were different types of immune cells infiltrated in the CT26 tumour, and we examined whether there was any difference in terms of other immune cell populations infiltration in the CT26 tumour after anti-BTNL2 mAb blockage." (PMID 35017553, 2022). "Interestingly, BTNL2 protein expression was significantly increased in LLC tumours after anti-PD-1 mAb treatment, mirroring the prior report in humans that BTNL2 expression was upregulated following anti-PD-1 treatment." (PMID 35017553, 2022). "Furthermore, we found that Vγ1 γδ T cell depletion decreased IL-17A secretion by CT26 tumour-infiltrating cells, with similar IL-17A secretion seen after treatment with anti-BTNL2 and controls." (PMID 35017553, 2022).
tumor (continued). "Interestingly, infiltration of CT26 and A20 tumours by γδT17 as well as serum IL-17A concentration were all greatly reduced following anti-BTNL2 mAb treatment compared to treatment with isotype control antibody." (PMID 35017553, 2022). "Furthermore, we find high BTNL2 expression in several human tumour samples from highly prevalent cancer types, which negatively correlates with overall patient survival." (PMID 35017553, 2022). "The significant therapeutic effect against this tumour suggests that antibody-mediated inhibition of BTNL2 may hold promise in combination with anti-PD-1/PD-L1 ICBs, and furthermore, may open the door to immunotherapy for tumours that have previously been considered “cold”." (PMID 35017553, 2022). "However, we cannot exclude the possibility that other cellular populations, for example, M2 macrophages or tumour-associated macrophages (TAM), also act downstream of BTNL2 to modulate anti-tumour immunity, therefore further investigation is needed to clarify this issue." (PMID 35017553, 2022). "Notably, BTNL2 mRNA induction was much greater than PD-L1 induction in LLC tumours, which may explain at least in part the significant impact of anti-BTNL2 mAb treatment on LLC tumour growth relative to anti-PD-1 mAb treatment." (PMID 35017553, 2022). "While the role of BTNL2 in protective immune response is becoming clearer, the functions of other BTNL molecules in anti-tumor immunity require further clarification." (PMID 37240071, 2023). "Flow cytometric analysis of the TME indicated that BTNL2 was primarily expressed on CD45- tumour cells; however, 48.47% of CD45+ leukocytes did also express BTNL2." (PMID 35017553, 2022). "Expression of BTNL2 mRNA was significantly induced in engrafted LLC and CT26 tumours compared to primary tumour cells, which was similar to PD-L1 mRNA induction." (PMID 35017553, 2022). "Therefore, it has been speculated that therapeutic targeting of MDSCs might offer significant additive or synergistic benefits when combined with ICB therapy, which is supported by our finding that dual-inhibition of PD-1 and BTNL2 bolsters anti-tumour immune responses." (PMID 35017553, 2022). "BTNL2 inhibition led to decreased MDSC infiltration, but an increased accumulation of CD8+IFN-γ+ T cells, in the TME in the A20 tumour model." (PMID 35017553, 2022). "In the current study, we found that BTNL2 blockade reduced MDSC infiltration of the TME, which we found was primarily mediated by IL-17A production by tumour-infiltrating γδ T cells." (PMID 35017553, 2022). "In addition, magnesium homeostasis is also closely related to the expression of immune activation genes in tumor microenvironment, such as TNFRSF13C, BTNL2, TNFSF4 and so on, thus promoting anti-tumor immune response." (PMID 41174507, 2025). "We found that BTNL2 was robustly and exclusively expressed by tumour cells, and was almost not expressed in the para-cancerous tissue." (PMID 35017553, 2022).
cancer (7 papers, 2022 to 2024). A tumor composed of atypical neoplastic, often pleomorphic cells that invade other tissues. "Intriguingly, it has also been reported that polymorphic variants of BTNL2 are associated with susceptibility to several autoimmune diseases and cancer, including lung and prostate adenocarcinoma." (PMID 35017553, 2022). "Moreover, RBMX was significantly positively associated with CD200, CD276, and butyrophilin like 2 (BTNL2) expression in most types of cancer." (PMID 38214653, 2024). "We expanded our investigation to include other cancer types, and found that BTNL2 was indeed widely expressed, with expression detected in all of the examined human cancer samples." (PMID 35017553, 2022). "Our findings make clear that BTNL2 is a promising therapeutic target in the ongoing effort to broaden and enhance cancer immunotherapy." (PMID 35017553, 2022). "CTLA-4 and BTNL2 are also upregulated, which proves that BTNL2 may also be part of a novel immune escape mechanism in cancer." (PMID 36793048, 2023). "We therefore tested the hypothesis that a correlation might exist between BTNL2 expression level and patient outcomes in these two cancer types." (PMID 35017553, 2022). "New clinical evidence shows that BTNL2 expression is elevated following anti-PD-1 treatment, lending credence to the concept that it may play a crucial role in a novel mechanism of cancer immune escape." (PMID 36359832, 2022). "In summary, we report that BTNL2 is a promising cancer immunotherapeutic target, with potential to enhance the efficacy of currently available immunotherapies, and possibly also to offer alternative stand-alone therapy in patients who are resistant to the current cancer immunotherapy." (PMID 35017553, 2022). "One recent clinical study found that the expression of BTNL2 and other immune checkpoint molecules, including CTLA-4, was increased following anti-PD-1 therapy, further suggesting that BTNL2 may represent a novel mechanism of cancer immune evasion." (PMID 35017553, 2022).
immune diseases (1 paper, 2020). "Thus, BTNL2 is the first member of the butyrophilin family that regulates T‐cell activation, which has implications in immune diseases and immunotherapy." (PMID 31605414, 2020).
BTNL2 also shares sentences with these, for which no sentence is quoted: infection (7 papers); myositis (3); type 1 diabetes (3); meningitis (2); alopecia areata (1); Arthritis (1); atopic asthma (1); autoimmune thyroid disease (1); bacteremia (1); Behcet disease (1); beryllium disease (1); cardiac sarcoidosis (1); cerebral malaria (1); chronic hepatitis B virus infection (1); colon cancer (1); colonic tumors (1); diabetes (1); Graves disease (1); IgA nephropathy (1); Legionnaires' disease (1); lung carcinoma (1); lung neoplasm (1); malignant melanoma (1); Mendelian diseases (1); multiple myeloma (1); myocarditis (1); neonatal lupus (1); neuroblastoma (1); osteoarthritis (1); osteoporosis (1).
A further 3 diseases each share a sentence with BTNL2 in 1 paper.